EPCAM (epithelial cell adhesion molecule)
Diseases named in the same sentence as EPCAM in open-access papers (continued):
Sharing a sentence is not in itself a finding about the gene and the disease.
tumor (continued). "To learn more about the PT and the RT, we analyzed EpCAM and CD49f expression on both tumor types and on tumors 6 days after dox withdrawal, using flow cytometry." (PMID 35398967, 2022). "In the current research, miRNA sequencing analysis was used to confirm the functional miRNAs encapsulated in tumor derived exosomes that contribute to elevated CD45+EpCAM+ cell apoptosis." (PMID 35711455, 2022). "At that time, tumors were collected and PKH26+ were separated from PKH26− cells by fluorescence-activated cell sorting (FACS) upon additional labeling with anti-human EpCAM antibody, in order to avoid contamination with non-tumor cells." (PMID 36077264, 2022). "Similar to EpCAM, c-Met also has a putative role in the acquisition of the stem cell status and EMT in cancer that causes tumor cell dissociation and metastasis." (PMID 35986321, 2022). "A cytolytic fusion protein targeting EpCAM illustrated a remarkable tumor inhibiting ability in a human TNBC cell-derived xenograft mouse model." (PMID 35414783, 2022). "In this study, we report the presence of CD45+EpCAM + cells in NSCLC tumor tissue, and these cells are prone to undergoing apoptosis." (PMID 35711455, 2022). "EpCAM is widely used as a selection marker for tumor cell identification and isolation in both human and mouse studies." (PMID 36077658, 2022). "Activation markers CD25 and CD69 were downregulated after NECA treatment and AB928 reversed this effect, both for cocultures with antigen expressing tumour cells or recombinant EpCAM stimulation." (PMID 36266575, 2022). "Across all EpCAM+ tumor cell lines, the EpCAM/CD16A ICE® exhibited the highest potency, and the EpCAM/NKp46 ICE® and anti-EpCAM Fc-enhanced IgG1 had potencies falling in the similar concentration range." (PMID 35225870, 2022). "In fact, the CD44+CD24+EpCAM+ phenotype was reported to exhibit a 100-fold increase in the tumor-initiating capacity versus the other cancer cells, both in vitro and in vivo." (PMID 36142575, 2022). "The EpCAM BiTE secreted from infected malignants effectively mediated the binding of EpCAM-positive tumor cells and CD3ε on T cells, which led to activation of naive T-cell and the release of cytokines, such as IFN-γ and IL-2." (PMID 36451817, 2022). "The diversity of all of these findings can be due to the different biological functions of EpCAM CSC marker in different tumor types, particularly CRC." (PMID 35016698, 2022). "Our current study reported the presence of CD45+EpCAM+ cells not only can be detected in the tumor tissue of patients but also in the PBMCs of these patients." (PMID 36147748, 2022). "Epithelial cell adhesion molecule (EpCAM) was earlier considered as a marker for adult liver stem/progenitor cells and oval cells, which is an epithelial cell adhesion molecule with all the characteristics of tumor stem cells (CSCs)." (PMID 36132125, 2022). "After Vicinium targets EpCAM on tumor cells, it is internalized, receives the cleavage of the linker, releases the payload exotoxin, and exhibits cytotoxicity." (PMID 35735360, 2022). "In an analysis of a tumor cell/immune cell mixture, a clean separation between tumor (HER2+/EpCAM+/MUC1+/EGFR+) and immune cells (CD45+) was observed." (PMID 35508767, 2022). "Catumaxomab consists of mouse IgG2 and rat IgG2b and targets CD3 on T cells and EpCAM on tumor cells." (PMID 36341333, 2022). "A study by Zheng and colleagues explored the impact of linker rigidity in the context of a bsApt with affinity for two different tumor cell antigens (EpCAM and CD44)." (PMID 35141049, 2022). "The EpCAM-specific types of these peptides have shown promising anti-tumor results and are being further investigated." (PMID 35986321, 2022). "It uses the Triomab molecular pattern and relies on two antigen-binding arms to bind the CD3 site of cytotoxic T cells and the EpCAM site of tumor cells respectively, thereby guiding T cells to kill target cells." (PMID 36341333, 2022).
tumor (continued). "The high-affinity NK cell and EpCAM/CD16A ICE® complexes were superior to those engaging NKG2D or NKp46 receptors when tested for the NK-cell-mediated elimination of EpCAM-expressing tumor cells." (PMID 35225870, 2022). "A disadvantage of EpCAM directed therapy is dose-dependent off-tumour on-target pulmonary toxicity secondary to alveolar EpCAM expression." (PMID 35158771, 2022). "EpCAM plays a different role as an oncogenic and/or tumor suppressor gene depending on its microenvironment in different tumor types." (PMID 35016698, 2022). "To that end, we utilized MCF-7 tumor cells expressing high levels of EpCAM to mimic tumor cells with an epithelial-like phenotype, incubating 105 MCF-7 cells with different nanoparticle preparations for 40 min." (PMID 35198544, 2022). "The QD450/EPCAM cells were added with EMT markers (QD615/CD44) because EpCAM+ cells are escaping tumor cells derived from primary tumor tissue and are most likely to be mesenchymal EpCAM+ cells." (PMID 35393460, 2022). "The interactions between the engineered bacteria and HEK293 cells that overexpress tumor antigens EpCAM or HER-2 were investigated by fluorescent staining and confocal microscopy." (PMID 35155394, 2022). "The tumours also all expressed markers of progenitors/biliary cells including Krt19, epithelial cell adhesion molecule (EpCAM), and A6." (PMID 35243280, 2022). "Currently, two ongoing clinical trials are evaluating the anti-tumor activity of EpCAM-based CAR T (NCT03013712, NCT02729493) in primary or refractory liver cancer." (PMID 36293184, 2022). "Although EpCAM/NKG2D ICE®-mediated EpCAM+ target tumor cell lysis showed a concentration-dependent pattern, the calculation of mean EC50 and Emax values was not feasible due to a nonlinear regression model producing no sigmoidal dose–response curves." (PMID 35225870, 2022). "In co-cultures of BC cell lines with human macrophages, a double-positive myeloid–tumoral hybrid population (CD11b+EPCAM+) was detected after 48 h, which indicates BC cell–macrophage fusions known as tumor hybrid cells (THC)." (PMID 35053451, 2022). "The EpCAM+ve tumor cell compartment represented the majority of both baseline and cultured HNSCC samples." (PMID 36097280, 2022). "Stem cell status has been identified in different groups of EpCAM+ circulating tumor cells (CTCs), and the detection of this status has proved to be beneficial to evaluate the response to sorafenib." (PMID 35911718, 2022). "Molecular imaging agents that target EpCAM would be potentially useful in the detection of epithelium-derived tumours." (PMID 36182995, 2022). "After quality control, 11,390 tumor cells (TG, EPCAM, KRT18, and KRT19) and 6,808 normal cells (TG, TPO) were obtained for subsequent analysis." (PMID 35359404, 2022). "Adecatumumab, which has a moderate affinity to EpCAM, can target tumor cells with high EPCAM expression and reduce aggression and metastasis in patients with fewer side effects." (PMID 35986321, 2022). "Meanwhile, the epithelial cell adhesion molecule (EpCAM), a cell surface molecule, is found to be overexpressed in the majority of human epithelial cancers and improve tumor invasion." (PMID 36612163, 2022). "The presence of THCs (CD45+CD14+EpCAM+) was observed in paired tumour, peritumour and metastasis tissue samples from CRC patients." (PMID 35884505, 2022). "Subsequently, we mined the TIMER database to explore the correlation between the expression of EpCAM and tumor-infiltrating immune cells including B cell, CD4+ T cell, CD8+ T cell, macrophage, neutrophil, and dendritic cell." (PMID 35517503, 2022). "It was worth mentioning that the 10 mg/kg EpCAM mAb group eliminated the tumor growth on the xenograft mouse model." (PMID 35281893, 2022). "This indicates that we can detect the majority of tumor cells in a sample with anti-EpCAM/anti-EGFR antibodies." (PMID 36613466, 2022).
tumor (continued). "We recently demonstrated that combinatorial treatment with AKT and mTOR inhibitors results in reduced tumor growth and increased survival of mice after subcutaneous transplantation of EpCAM+ Huh7 cells." (PMID 35454789, 2022). "Immunoaffinity-based capture methods generally facilitate the isolation of CTCs through the binding of EpCAM, which is expressed at high levels on the surface of many such tumor cells." (PMID 35198544, 2022). "Epithelial cell adhesion molecule (EpCAM) is a tumor marker widely used in both basic studies and clinics." (PMID 36077658, 2022). "EPCAM+/FOLR1- cells had a larger proportion in tumor samples, while there were more EPCAM-/FOLR1+ cells in normal lung tissues." (PMID 36249427, 2022). "These nanoparticles were coupled with anti-EpCAM, allowing them to precisely detect tumor cells in blood samples from metastasis tumor patients when exposed to an external magnetic field." (PMID 36085575, 2022). "The EpCAM expression level is generally believed to indicate the epithelial-mesenchymal transition status and is related to tumor metastasis and progression." (PMID 35136652, 2022). "Cisplatin-resistant tumor cells consist of a higher proportion of epithelial cell adhesion molecule (EpCAM) and induce the expression of IL-6 and tumorigenic cytokines that contribute to cisplatin-induced stemness." (PMID 35945195, 2022). "The CD3×EpCAM BsAb eliminated the tumor cells with high EpCAM expression level, activated T cells and induced T cells redirected to tumor cells in vitro." (PMID 35281893, 2022). "Apart from carcinomas, for osteosarcoma-derived exosomes, analysis of EpCAM, CD63 and vimentin expression levels has exceeded traditional histological biopsy with high specificity and accuracy, as well as a low risk of tumor spread." (PMID 36369033, 2022). "Circulating tumor cells (CTCs) can also express EpCAM antigen and a nanoprobe or sensor can be developed to study the presence of these biomarkers on cancer cells by using anti-EpCAM antibody." (PMID 36140116, 2022). "EpCAM expression plays a crucial role in the metastatic progression of tumours by preventing cell–cell adhesion and facilitating cell migration, proliferation and differentiation." (PMID 35158771, 2022). "So, tetraspanins were analysed in plasma together with EpCAM, an epithelial marker commonly used to identify epithelial cancer circulating tumour cells." (PMID 35135541, 2022). "As the CCH is typically shed from tumor tissue, it is critical to examine the EMT/MET cancer stem cell markers status for EpCAM+ in addition to tumor location." (PMID 35393460, 2022). "In KDM2A-deficient cells, TET2 upregulation can induce the reactivation of two tumor-suppressive genes, epithelial cell adhesion molecule and e-cadherin located downstream of TET, and thus inhibiting cell migration and invasion." (PMID 35223782, 2022). "The overexpression of EpCAM was demonstrated in 54% of specimens with more than 5 cm tumor size (P = 0.02)." (PMID 35016698, 2022). "EPCAM is a human cell surface glycoprotein and plays crucial roles in tumor biology, especially CRC." (PMID 36542699, 2022). "As effector cells, PBMCs were obtained from healthy donors, and as target cells, a group of tumor cells with different EpCAM expression levels were chosen." (PMID 35281893, 2022). "EpCAM+ circulating tumor cells isolated from primary human luminal BC patients’ blood contain metastasis-initiating cells, leading to bone, lung, and liver metastasis in mice." (PMID 35392236, 2022). "Using the anti-EpCAM antibody-covered wire, we detected CTCs in three out of six samples from the local tumor patients." (PMID 35054482, 2022). "Expression levels of EpCAM were analyzed in tumor cell lines 1 h and 24 h after co-culture with platelets." (PMID 35265204, 2022).
tumor (continued). "Consequences in tumor cell behavior after interaction with platelets was studied in terms of EpCAM protein expression, gene expression of EMT and stemness markers and cell growth." (PMID 35265204, 2022). "There was a clear trend of EpCAM expression reduction after 1 h of co-culture with platelets in all tumor types analyzed (prostate, lung, colorectal and breast), being significant in PC3, 22RV1, H1975, MCF7 and MDA-MB-231 cell lines." (PMID 35265204, 2022). "Of note, Emp1-TOMhigh tumor buds and micrometastases were labeled with EPCAM and E-CADHERIN, implying that they retained an epithelial organization." (PMID 36352230, 2022). "The modified LNPs resulted in the efficient delivery of siRNA-EpCAM when targeted against epithelial cell adhesion molecule (EpCAM) Epi-1, positive cells in vitro and also minimized the progression of tumour in mice." (PMID 36432711, 2022). "Most of the studies were devoted to the expression of EpCAM in tissues of epithelial-derived neoplasms." (PMID 35208477, 2022). "Both IHC and IF staining results showed that the expression of CD31, RhoJ, EpCAM, and moesin were significantly increased in tumor tissues derived from the RhoJ-overexpressing group." (PMID 35173528, 2022). "On the basis of the CellMarker dataset and our previous studies, tumor cells (marked by EPCAM and SOX4) were isolated from other cell populations through dimensionality reduction and unsupervised clustering analysis." (PMID 35505963, 2022). "Specifically, the tumor epithelium (EpCAM), stromal compartment (FAP), immune cells (CD45) and proliferation (Ki67) were analyzed in baseline and 48 h after culturing (representative images from two cases are displayed)." (PMID 36097280, 2022). "It is well established that c-Met uses the PAM axis to regulate tumor cells’ critical functions, such as proliferation and survival; on the other hand, some studies have proven that EpCAM uses the same axis for carcinogenesis." (PMID 35986321, 2022). "Antibodies against surface EpCAM are routinely used to capture CTCs from blood, but such an approach is inherently limited to tumor cells with epithelial differentiation." (PMID 36358657, 2022). "EPCAM (also known as Trop1 or CD326) is a type I transmembrane glycoprotein that was originally identified as a novel tumor-specific antigen highly expressed on the surface of many carcinoma cells." (PMID 35730316, 2022). "The epithelial cell adhesion molecule (EpCAM) is a type I transmembrane and glycosylated protein, which is overexpressed in many neoplasms." (PMID 34240826, 2022). "Following culture in the presence of TASCs, EpCAM+ tumor cells were sorted and their expression of EMT-related genes was quantified by qRT-PCR." (PMID 35454931, 2022). "Remarkably, higher levels of OSMR are expressed in epithelial-cell-adhesion-molecule (EpCAM)-positive tumor cells displaying CSC properties." (PMID 36077744, 2022). "Among all the markers, EpCAM has been referred to as a universal molecular marker for the detection of circulating tumor cells (CTCs) by the CellSearch system (Veridex, Warren, NJ, USA)." (PMID 36142574, 2022). "In a further step, we evaluated the effect of FOLFOX-treated CAFs on re-transplant ability of isolated colorectal patient tumor CD44v6(+)EpCAM(+)CD133(+)ALDH1(+) cells (CD44v6(+) CICs)." (PMID 35982950, 2022). "Correspondingly, attachment of indolinobenzodiazepine pseudodimers (IGN) to EpCAM (EpCAM-IGN) antibodies exhibited dose-dependent anti-tumor activity." (PMID 36369033, 2022).
tumor (continued). "The hijacking of sinusoidal blood vessels by tumor cells in RHGP lesions has been reported in both preclinical and clinical CRCLM cases, and EpCAM+ tumor cells infiltrating the sinusoidal blood vessels are considered to indicate vessel co-option." (PMID 35951441, 2022). "Their study found that the amount of the exosomal tumour marker EpCAM was much higher in the plasma of breast cancer patients than in healthy controls." (PMID 35630197, 2022). "EpCAM has been reported to be overexpressed in several tumors, which correlates with poor prognosis, therapeutic failure, and early tumor recurrence." (PMID 35735360, 2022). "EpCAM, along with β-catenin, helps to regulate Myc, whose aberrant expression in tumor cells enablesitto bypass the cell cycle, resulting in uncontrolled proliferation." (PMID 36428553, 2022). "Oportuzumab monatox (OM), an ADC that uses Pseudomonas exotoxin A (ETA 252-608) as a cytotoxic agent and targets EpCAM expressing tumor cells, has shown potential as an intravesical therapeutic agent." (PMID 35677058, 2022). "The percentage of MCT4+EpCAM+, PD-L1+EpCAM+, and MCT4+PD-L1+EpCAM+ cells in tumor tissues was higher than 50% as shown in typical case 2, and EpCAM was used as a marker for poor prognosis of TNBC." (PMID 36199799, 2022). "To further understand the morphological and histological characteristics of GC organoids, we performed an immunofluorescence analysis on the tumor epithelial adhesion molecule EpCAM and the tumor stem cell marker CD133." (PMID 35013129, 2022). "As an activator of the WNT pathway, EpCAM is thought to have a direct relationship with tumor progression." (PMID 36451817, 2022). "The CD3×EpCAM BsAb had similar pharmacokinetic parameters with EpCAM mAb and inhibits tumor growth on the SW480 tumor cell xenograft mouse model." (PMID 35281893, 2022). "EMT is a process in which epithelial tumor cells lose their adhesion capacities due to the downregulation of the epithelial cell adhesion molecule (EpCAM) expression and acquire mesenchymal characteristics that promote cell motility and invasiveness." (PMID 35884432, 2022). "EpCAM (epithelial cell adhesion molecule, CD326) has also been described as a reliable marke for the isolation of disseminated tumor cells in the bone marrow and lymph nodes of HNSCC." (PMID 36424557, 2022). "Herein, we systematically investigated the antitumor efficacy of this recombinant virus in different solid tumor models and found that VV-EpCAM BiTE results in superior tumor suppression effects compared to VV-Ctrl in EpCAM-positive tumor cells." (PMID 36451817, 2022). "Re-analyzing tumor cells selected for high EpCAM expression revealed 11 different clusters, revealing heterogeneity within tumor cells." (PMID 35626115, 2022). "The result showed that Fibro-subcluster 1 enriched iCAFs, named iCAFs-enriched cluster, and Fibro-subcluster 2 enriched mCAFs, because it highly expressed EPCAM, thus we identified it as mCAFs-enriched tumor cluster." (PMID 35794563, 2022). "CD44 and EpCAM peptide-loaded DCs vaccines were also evidenced to endow dramatic anti-tumor immunity to HCC cells." (PMID 36293184, 2022). "DARP EC1 binds to the EpCAM receptor with a picomolar affinity (Kd = 68 pM).EpCAM, a transmembrane glycoprotein with a molecular weight of 40 kDa andconsisting of 314 amino acid residues, was first discovered as a tumor antigenin colon cancer cells in 1979." (PMID 35441046, 2022). "So far, it is unclear that how EpCAM expression is strong upregulated in tumor cells but sometimes diminishes." (PMID 36077658, 2022). "In other words, CD166, dependently, and EpCAM were identified as putative CSC markers with greater tumor progression and aggressiveness in human CRC specimens." (PMID 35016698, 2022). "EpCAM is a potential biomarker for neoplasms of epithelial origin and a homotypic calcium-independent cell adhesion molecule." (PMID 35719973, 2022).